RNU6-85P (RNA, U6 small nuclear 85, pseudogene)
Gene: Small nuclear RNA gene on chromosome 7 (140,884,072 to 140,884,178, forward strand). Ensembl gene ENSG00000271932.
Homologues: Orthologues: chimpanzee U6 (100% identical), macaque U6 (95% identical). Paralogues in human: RNU6-38P (90% identical), RNU6-393P (89% identical), RNU6-1145P (88% identical), RNU6-116P (88% identical), RNU6-187P (88% identical), RNU6-39P (88% identical), RNU6-698P (88% identical), RNU6-842P (88% identical), RNU6-1011P (87% identical), RNU6-1316P (87% identical), RNU6-25P (87% identical), RNU6-29P (87% identical), and 1288 more.